POGZ (pogo transposable element derived with ZNF domain)
Diseases named in the same sentence as POGZ in open-access papers:
POGZ is named in the same sentence as 49 diseases in open-access papers, as found by Europe PMC text mining. Sharing a sentence is not in itself a finding about the gene and the disease. The quoted sentences say what the papers report.
Intellectual disability (18 papers, 2016 to 2026). "White–Sutton syndrome (WSS), associated with POGZ gene mutations, is a rare genetic disorder characterized by a spectrum of phenotypic features, including intellectual disabilities, developmental delays, and epilepsy." (PMID 40051906, 2025). "White–Sutton syndrome is an autosomal dominant disease caused by a POGZ variant encompassing a combination of intellectual disability, developmental retardation, facial dysmorphism, hypotonia, autism spectrum disorder and behavioral abnormalities." (PMID 37535131, 2024). "Heterozygous loss-of-function mutations in the human POGZ gene are associated with intellectual disability and autism spectrum disorder." (PMID 33306669, 2020). "Specifically, studies analyzing the genetic basis of autism spectrum disorders (ASDs) and intellectual disability have detected inactivating mutations in POGZ in some of these patients." (PMID 29898395, 2018). "Individual BAB2330 and four other carriers of heterozygous truncating variants in POGZ allowed the recent description of a new syndromic form of intellectual disability." (PMID 27799067, 2016). "While variations in the POGZ gene have been associated with intellectual disabilities and developmental delays in humans, the exact pathophysiological mechanisms remain unclear." (PMID 38534384, 2024). "POGZ has been associated with intellectual disability and autism spectrum disorders, and plays a role in modulating chromatin structure; however, the biological role of POGK is unknown." (PMID 36688327, 2023). "Interestingly, POGZ is one of the most recurrently mutated genes in patients with neurodevelopmental disorders and neuropsychiatric disorders, including schizophrenia, neuroectodermal-derived intellectual disability, and ASD." (PMID 35650610, 2022). "TGex analysis (LifeMap Sciences, USA) prioritized 9 candidate variants across 7 genes (MED13, POGZ, SETBP1, SCN9A, SCO1, APTX, TIE1) associated with phenotypes including congenital megacolon, intellectual disability, motor delay, and developmental delays." (PMID 41195223, 2025). "The POGZ gene has been found frequently mutated in neurodevelopmental disorders (NDDs), particularly autism spectrum disorder (ASD) and intellectual disability (ID)." (PMID 35650610, 2022). "Over time, POGZ variants have been identified in patients with autism spectrum disorder (ASD), moderate to severe intellectual disability (ID), and schizophrenia." (PMID 34206215, 2021). "De novo likely gene‐disrupting variants of POGZ cause autism spectrum disorder (ASD) and intellectual disability." (PMID 31347273, 2019). "A recent study explored the role of the gene POGZ in intellectual disability and autism, and this analysis included an examination of spatiotemporal expression patterns of POGZ in BrainSpan and GTEx." (PMID 28011779, 2017).
autism spectrum disorder (14 papers, 2016 to 2024). A spectrum of developmental disorders that includes autism, and Asperger syndrome. "POGZ is a recently identified high confidence (hc) autism spectrum disorder (ASD) gene with at least two dozen de novo loss-of-function (LoF) variants." (PMID 33334860, 2021). "POGZ mutations that disrupt the DNA-binding activity of POGZ are also associated with Autism spectrum disorder (ASD)." (PMID 31335867, 2019). "Deleterious genetic variants in POGZ, which encodes the chromatin regulator Pogo Transposable Element with ZNF Domain protein, are strongly associated with autism spectrum disorder (ASD)." (PMID 34879283, 2021). "De novo mutations in pogo transposable element with zinc finger domain (POGZ) have been identified in six independent and diverse cohorts of individuals with NDDs ranging from autism spectrum disorder to developmental delay." (PMID 26739615, 2016).
autism (11 papers, 2017 to 2026). Persistent deficits in social interaction and communication and interaction as well as a markedly restricted repertoire of activity and interest as well as repetitive patterns of behavior. "Rare, inherited missense variants of POGZ associate with autism risk and disrupt neuronal development." (PMID 34206215, 2021). "It has been demonstrated that disruptions of POGZ are associated with autism, while inactivation of JRK in mice result in epileptic seizures, and JRK was found to be overexpressed in cancers." (PMID 32742312, 2020). "Remarkably, de novo regulatory genes (POGZ, NFIB) are previously identified autism risk genes in large scale sequencing studies, providing validation of dosage sensitivity mechanisms." (PMID 42281968, 2026). "POGZ protein enhances chromatin accessibility and expression of clustered synapse genes, and cooccurs loci with ADNP, a gene related with autism, according to analyses of POGZ knockout mice." (PMID 39775551, 2025). "Strong candidate genes such as CHD8, POGZ and DYRK1A were previously reported to be associated with not only autism but also gastrointestinal issues, facial dysmorpisms, visual and feeding problems." (PMID 33338084, 2020). "Additionally, 4 novel genes, POGZ, KDM5B, NAA15, and FRYL, harbored at least two de novo mutations in both CHD and autism cohorts." (PMID 34735430, 2021).
developmental delay (11 papers, 2016 to 2026). "Mutations in the POGZ gene cause White-Sutton syndrome, which has a highly variable phenotype including obesity, developmental delay, language and speech delay, motor delay, microcephaly, and non-specific vision problems." (PMID 38297031, 2024). "Pathogenic variants in POGZ are strongly associated with risk for NDDs such as ASD, ID, and Developmental Delay." (PMID 34879283, 2021). "POGZ gene which plays a role in cell cycle progression is also found to contribute to a subset of ASD with varying developmental delay, vision problems, motor coordination impairment, tendency of obesity, microcephaly, hyperactivity and feeding problems." (PMID 28702161, 2017). "Premature truncating mutations in pogo transposable element with zinc finger domain, or POGZ (MIM#614787), have been implicated by WES in three ASD cohort studies, cohorts examining developmental delay (DD) and ID and one schizophrenia cohort." (PMID 26739615, 2016).
white-sutton syndrome (11 papers, 2016 to 2025). An autosomal dominant non-syndromic intellectual disability that has_material_basis_in an autosomal dominant mutation of POGZ on chromosome 1q21.3. "White-Sutton syndrome is a rare genetic condition caused by denovo heterozygous pathogenic POGZ variants." (PMID 39775551, 2025). "POGZ gene expresses as multidomain nuclear protein associated with transcriptional control, and its inadequate function has recently been linked to White-Sutton syndrome, a syndromic neurodevelopmental condition, identified in proband ES-4." (PMID 39775551, 2025). "Subsequent GS revealed an additional pathogenic SNV in POGZ, associated with White-Sutton syndrome, and a 15q11.2 deletion overlooked by the initial microarray." (PMID 40225944, 2024). "White-Sutton syndrome is an autosomal dominant neurodevelopmental disorder caused by heterozygous mutation in POGZ (Pogo Transposable Element Derived with ZNF Domain)." (PMID 37016333, 2023). "De novo disruptive mutations of POGZ are associated with White-Sutton syndrome, a syndromic neurodevelopmental disorder characterized by developmental delay, cerebral malformation, hearing loss, facial dimorphisms, and seizures." (PMID 37016333, 2023). "POGZ variants cause White-Sutton syndrome, yet another dominant neurodevelopmental disorder with dysmorphic features." (PMID 37234784, 2023). "A review of the current literature revealed 18 cases of White-Sutton syndrome with POGZ variants and congenital heart disease, and we summarize their clinical features in this study." (PMID 37016333, 2023). "White-Sutton syndrome represents a wide and variable spectrum of symptoms and abnormalities related to variants or copy number variations in POGZ gene." (PMID 35052493, 2022). "Mutations in POGZ are associated with the White-Sutton syndrome, which is a neurodevelopmental disorder characterized by delayed psychomotor development and a characteristic constellation of dysmorphic facial features." (PMID 34356170, 2021). "POGZ deficiency causes a variety of neurodevelopmental diseases, including White-Sutton syndrome." (PMID 39775551, 2025). "Herein, we present a case of White-Sutton syndrome with a novel POGZ frameshift mutation." (PMID 37016333, 2023). "Consistent with the hypothesis of expanded phenotypes, the phenotypic variability of White-Sutton syndrome associated with variants in POGZ keeps extending with clinical features including ASD, DD, ID, schizophrenia, and microcephaly." (PMID 27799067, 2016). "Patient 17 had a de novo frameshift mutation in the POGZ gene, which is associated with White-Sutton syndrome (WHSUS, OMIM 616364)." (PMID 40589517, 2025). "POGZ dysfunction leads to a wide spectrum of neurodevelopmental disorders, also referred to as White-Sutton syndrome." (PMID 35052493, 2022).
microcephaly (9 papers, 2016 to 2026). A congenital or acquired developmental disorder in which the circumference of the head is smaller than normal for the person's age and sex. "As some human individuals with POGZ mutations show microcephaly, we also measured total brain weight at P11, and found a significantly lower brain weight in Pogz-deficient mice (P = 0.0042)." (PMID 33203851, 2020). "The description of the five individuals and a review of eight patients from the literature indicate that individuals with mutations in POGZ are likely to have global DD, microcephaly, ID, strabismus and variable hearing loss." (PMID 26739615, 2016). "Similar to POGZ, many genes encoding proteins required for proper centrosomal function or chromosome segregation are mutated in patients with microcephaly, demonstrating a common theme of aberrant neuronal proliferation and migration." (PMID 26739615, 2016). "These functions of POGZ are consistent with the presence of deleterious variants in patients with microcephaly and other neurodevelopmental phenotypes." (PMID 26739615, 2016). "Additionally, a recently published case report details a missense POGZ mutation present in an individual with microcephaly, ASD, ID, and other clinical features." (PMID 26739615, 2016). "When POGZ was knocked out in both excitatory and inhibitory neurons within the neuronal system, the mice exhibited notable phenotypes, such as dwarfism, microcephaly, and motor deficits." (PMID 38534384, 2024).
Obesity (5 papers, 2017 to 2024). Accumulation of substantial excess body fat. "Some individuals with mutations in POGZ were reported to have obesity and skeletal anomalies, which agrees with the enrichment of differentially expressed genes in metabolism and abnormal skeleton morphology." (PMID 33203851, 2020).
osteosarcoma (4 papers, 2019 to 2024). A usually aggressive malignant bone-forming mesenchymal neoplasm, predominantly affecting adolescents and young adults. "For instance, high expression of POGZ is reportedly associated with a poor prognosis of osteosarcoma, while JRK expression was aberrantly elevated in colorectal, breast, and ovarian cancers." (PMID 36421335, 2022).
congenital heart disease (2 papers, 2023 to 2024). A heart disease that is present at birth. "Computed tomography (CT) scanning of Q1038R homozygous mouse embryos (E15.5) showed a ventricular septal defect, which was suspected of causing embryonic lethality, suggesting the relationship between congenital heart disease and POGZ mutation." (PMID 38534384, 2024). "Our findings based on the present case and those in the literature indicate a relationship between POGZ mutation and congenital heart disease." (PMID 37016333, 2023). "In addition, congenital heart disease is reported to be associated with POGZ haploinsufficiency in some cases." (PMID 38534384, 2024).
schizophrenia (2 papers, 2016). A major psychotic disorder characterized by abnormalities in the perception or expression of reality. "To date, seven de novo mutations leading to premature termination of POGZ have been identified in cohorts of individuals with diverse NDDs, including ASD (N = 3), ID (N = 6), DD (N = 2), or schizophrenia (N = 1)." (PMID 26739615, 2016).
coloboma (1 paper, 2025). An abnormality in which a part of a structure in one or both eyes is missing. "Although classified as VUS, bioinformatic analysis and rarity in databases underscore POGZ as an interesting candidate gene for congenital eye malformations and the possible association of White–Sutton Syndrome with coloboma." (PMID 41155148, 2025). "POGZ is linked to White–Sutton syndrome, a rare neurodevelopmental disorder with variable features including ocular anomalies, such as retinal dystrophies; colobomas have only described in isolated (n = 3) patients." (PMID 41155148, 2025).
Gabriele de Vries syndrome (1 paper, 2025). "POGZ gene codes for pogo transposable element-derived zinc-finger protein and YY1 gene regulates transcription, chromatin, and RNA-binding proteins that have been associated with White Sutton and Gabriele-de-Vries syndromes, in recent data." (PMID 39775551, 2025).
Huntington disease (1 paper, 2022). Huntington disease (HD) is a rare neurodegenerative disorder of the central nervous system characterized by unwanted choreatic movements, behavioral and psychiatric disturbances and dementia. "KEGG analysis of POGZ targets revealed the enrichment of terms such as pathways of neurodegeneration, Parkinson and Huntington diseases." (PMID 35650610, 2022).
hydronephrosis (1 paper, 2024). Collection of urine in the renal pelvis that results in dilatation of the renal pelvis and calyces. "Some of the CAKUT cases with associated malformations did reveal a pathogenic variant in WES (unilateral renal agenesis Hypomethylation C2; horseshoe kidney KMT2A; hydronephrosis FREM2, KANSL1; LUTO CHD7; renal hypoplasia GREBIL, POGZ)." (PMID 37535131, 2024).
Noonan syndrome (1 paper, 2018). Noonan Syndrome (NS) is characterized by short stature, typical facial dysmorphism and congenital heart defects. "Four patients who carried LGD variants in known DD genes (POGZ, ARID1B, FOXP1, and SIN3A) and one patient who carried a known activating variant in the Noonan syndrome gene PTPN11 were considered pathogenic variants by the American College of Medical Genetics and Genomics guidelines." (PMID 30532227, 2018).
neurodevelopmental disorder (14 papers, 2016 to 2025). A behavioral and cognitive disorder with onset during the developmental period that involves impaired or aberrant development of intellectual, motor, or social functions. "Genetic analysis revealed a heterozygous mutation in the pogo transposable element derived with zinc finger domain (POGZ) gene – a gene implicated in neurodevelopmental disorders – suggesting this variant contributed to her neurobiological vulnerability." (PMID 40746129, 2025). "The down-regulation of neural lineage genes was of great interest to us, provided that mutations of POGZ are known frequently linked with neurodevelopmental disorders." (PMID 35650610, 2022). "POGZ therefore regulates the transcription of genes that promote synapse formation and function, including several that are implicated in neurodevelopmental disorders." (PMID 34879283, 2021). "De-novo mutations in POGZ (cg09988380) are causal for neuropsychiatric and neurodevelopmental disorders." (PMID 33883019, 2021). "While POGZ has been associated with neurodevelopmental disorders in large cohort studies, our data suggest that loss of function variants in POGZ lead to an identifiable syndrome of NDD with specific phenotypic traits." (PMID 26739615, 2016). "Our study suggests that gain-of-function or dominant negative effect through escaping NMD and the location of the variants in the prolin-rich domain of the protein may play an important role in the severity of manifestations of POGZ–associated neurodevelopmental disorders." (PMID 35052493, 2022). "We further demonstrate that POGZ forms a nuclear complex and co-occupies loci with ADNP, another high-confidence ASD risk gene, and provide evidence that POGZ regulates other neurodevelopmental disorder risk genes as well." (PMID 34879283, 2021). "We then chose two important neurodevelopmental disorder genes, POGZ and DEPDC5, to test this hypothesis." (PMID 33334860, 2021).
cancer (5 papers, 2019 to 2025). A tumor composed of atypical neoplastic, often pleomorphic cells that invade other tissues. "While the role of PogZ in cancer is poorly understood, this protein was reported to interact with HRP2 in cancer cells to facilitate DNA repair." (PMID 34685704, 2021). "We examine examples in detail, in particular the gene POGZ, which is disrupted in many of the cancer datasets and has an unusually large number of predicted targets, from which the network analysis predicts membership of cancer related pathways." (PMID 31335867, 2019). "Additional genes identified included GALNT10, NPIPB4, POGZ, MED13L and UGGT1, most of which had confirmed roles in cancers." (PMID 40507918, 2025). "All three genes (i.e., TRAT1, POGZ, and FMN1) have been identified as potential therapeutic targets for the treatment of some cancers." (PMID 38396979, 2024). "Thus the genomic disruption of POGZ in many of the cancer datasets used in our study and the concomitant changes in its expression, and the significant correlation of the expression changes of an unusually high number of targets, may indicate that POGZ has a functional role in cancer biology." (PMID 31335867, 2019).
brain diseases (1 paper, 2022). "Both GO and KEGG analyses show that POGZ target genes are overwhelmingly linked with neural differentiation, neuronal and synapse function, leaning, and brain diseases." (PMID 35650610, 2022).
POGZ also shares sentences with these, for which no sentence is quoted: epilepsy (3 papers); tumor (2); absence seizures (1); autosomal dominant disease (1); Brachycephaly (1); brain malformations (1); cardiofaciocutaneous syndrome (1); cervical carcinoma (1); cognitive deficits (1); congenital hydrocephalus (1); congenital megacolon (1); dwarfism (1); genetic disorder (1); glycine encephalopathy (1); Kabuki syndrome 1 (1); leukemia (1); lung adenocarcinoma (1); lymphoma (1); medulloblastoma (1); Motor delay (1); Mowat-Wilson syndrome (1); Multiple Myeloma (1); myoclonic atonic epilepsy (1); Neurodevelopmental delay (1); neurological disorders (1); ovarian carcinoma (1); Parkinson (1); polyneuropathy (1); retinal dystrophies (1); Rett syndrome (1).
A further 1 disease shares a sentence with POGZ in 1 paper.